DKK1 (dickkopf Wnt signaling pathway inhibitor 1)
Diseases named in the same sentence as DKK1 in open-access papers (continued):
Sharing a sentence is not in itself a finding about the gene and the disease.
colon carcinoma (continued). "The tumor suppressor function of DKK1 has been demonstrated in a colon cancer model, and epigenetic silence of DKK1 has been reported in colorectal cancers." (PMID 26799283, 2016). "Our data, however, provide an alternative explanation for the β-catenin-independent growth inhibitory effects of DKK-1 in DLD-1 colon carcinoma, H28 and MS-1 mesothelioma and HeLa cervical cancer cells." (PMID 25788273, 2015). "Next, we studied the expression of DKK-1 in human colon carcinoma cells both in vitro and in a large cohort of metastatic CRC patients." (PMID 25788273, 2015). "Our group has previously reported that DKK-1 gene expression is downregulated in colon cancer as compared to healthy adjacent tissue and that this is partially due to promoter methylation of the gene in advanced stages of progression (Dukes' C and D)." (PMID 25788273, 2015). "In colon cancer cells, DKK-1 inhibits proliferation both in vitro and in immunodeficient mice and its expression is linked to an E-cadherin-dependent adhesive phenotype, supporting a tumor suppressor role for this protein." (PMID 25788273, 2015). "Authors, analyzing 217 patients affected by colon cancer, found that Dkk1 expression was inversely correlated with tumor stage, the presence of metastasis, and recurrence." (PMID 24527460, 2014). "Previous studies have shown that the expression of DKK-1 was down-regulated significantly in human colon cancer, gastric cancer and melanoma." (PMID 24612589, 2014). "DKK-1 downregulation is due to promoter methylation in 24% of advanced colon tumors (Dukes’ stages C and D)." (PMID 24202444, 2013). "On the other hand, DKK1 was unmethylated in the early stage of colon cancer (Dukes’ B) and related cell lines including SW480 and HCT15." (PMID 22815877, 2012). "First, DKK1 gene expression was analyzed in available colon cancer cell lines to investigate the effects from genistein treatment." (PMID 22815877, 2012). "Our result showed a general decrease in phosphorylated H3 serine 10 by genistein within the DKK1 gene in the colon cancer cell lines tested." (PMID 22815877, 2012). "In DLD-1 cell line from Dukes’ C, a more advanced stage of colon cancer, demethylation of the DKK1 gene by 5-aza-2′-deoxycytidine, a DNMT inhibitor, re-activated DKK1 expression." (PMID 22815877, 2012). "The expression of DKK1 was silenced by promoter hypermethylation in the advanced stage of colon cancer (Dukes’ C and D)." (PMID 22815877, 2012). "In contrast to stimulating proliferation, Dkk1 appears to induce neural differentiation of embryonic SCs and differentiation of colon cancer cells." (PMID 21915302, 2011). "MiR-590-3p promoted colon cancer progression via WIF1 and DKK1, and it might be a promising biomarker for colon cancer treatment." (PMID 33439933, 2021). "Similarly, seocalcitol (EB1089), a vitamin D analog, has been shown to induce the expression of DKK-1 in colon cancer and pancreatic cancer, thereby demonstrating its therapeutic potential for cancer treatment." (PMID 34451907, 2021). "The primary objective of this study was to assess whether pre-operative treatment with decitabine can decrease methylation and increase the expression of WNT target genes APCDD1, AXIN2 and DKK1 in colon cancer patients." (PMID 34068407, 2021). "Moreover, the inhibition of brucine on colon cancer proliferation was related to Wnt/β-catenin signaling pathway, in which the expression of dickkopf-related protein 1 (DKK1) increased significantly, while the expression of β-catenin decreased." (PMID 32308621, 2020). "Increased DKK1 levels in later stages of colon cancer may be indicative of tumour invasion, differentiation and metastasis thus supporting a role of DKK1 as a prognostic factor." (PMID 27367730, 2016). "Previous studies have reported that overexpression of DKK1 is negatively correlated with the existence of VM, and may reduce proliferation, migration and invasion of colon cancer cells." (PMID 27240974, 2016).
colon carcinoma (continued). "Vitamin D analogues also inhibit the growth of xenograft models of human colon cancer and this effect was achieved through several mechanisms including increasing the production of DKK-1, a pure inhibitor of Wnt/β-catenin signalling, expression in the xenografts." (PMID 26205949, 2015). "However, since DKK-1 expression is regulated by beta-catenin, reduced beta-catenin activity results in reduced DKK-1 levels in Fra-1-depleted colon cancer cells." (PMID 26646695, 2015). "Thus, ALDH1A1 and REPS2 (mutated in 14/700, (2%) of colon tumors, and in 4/700, (0.57%) of colon tumors, respectively; Cosmic database) seem to be major mediators of nuclear DKK-1 effects." (PMID 25788273, 2015). "In colon cancer, DKK1 was found down-regulated, indicating the loss of a negative feedback control of the Wnt/β-catenin pathway in this neoplasia." (PMID 26264222, 2015). "However, DKK1 has also been shown to inhibit invasion and migration in colon cancer, breast cancer, and PC3 cells, indicating the complexity of studying this system in vitro." (PMID 26545120, 2015). "Similar to colon cancer, 1,25D3 dose-dependently increased expression of the extracellular canonical Wnt inhibitor, DKK-1, in R7 cells while loss of VDR in MMTV-Ron mice reduced tumoral DKK-1 mRNA." (PMID 26008979, 2015). "Our results suggest that abnormal up-regulated FoxM1-PTTG1 pathway may promote colon cancer through suppressing DKK1 and thereby enhancing the Wnt pathway." (PMID 26264222, 2015). "In disease, DKK1 is expressed by synovial fibroblasts, plasma cells, and colon cancer cells." (PMID 25548714, 2014). "However, paradoxically, the expression of DKK-1 was down-regulated significantly in human colon cancer, gastric cancer and melanoma." (PMID 25116444, 2014). "DKK1 is typically silenced in colon cancer and acute myeloid leukaemia (AML) by DNA hypermethylation that correlated with advanced stages of colorectal tumorigenesis and may be a useful prognostic marker in AML." (PMID 25144498, 2014). "Our group reported that DKK-1 expression is frequently downregulated in human colon cancer, which suggests that DKK-1 may act as a tumor suppressor gene in this neoplasia." (PMID 24202444, 2013). "Their study confirmed that DKK1 has inhibitory effects on colon cancer progression." (PMID 23922913, 2013). "The present study will contribute to the identification of the mechanistic basis behind the anticancer effects of genistein by presenting a novel relationship between the activation of DKK1 expression and histone acetylation at the gene region in early stage of colon cancer development." (PMID 22815877, 2012). "BAN construction using the genes differentially expressed in common between both colon cancer cell lines identified DKK1 as a highly interconnected node of the network, which could as such be a candidate druggable gene." (PMID 19732436, 2009). "Dikkopf homolog-1 (DKK1) is a highly interconnected node in the network generated with genes in common between the two colon cancer cell lines, and functional validations of this target using small interfering RNAs (siRNAs) showed a chemosensitization toward MTX." (PMID 19732436, 2009). "The presence of a fraction of DKK-1 within the nucleus controlling gene expression might contribute to explain the recently proposed role of DKK-1 to inhibit colon cancer-initiating cell growth through mechanisms other than the blockade of the Wnt/β-catenin signaling pathway." (PMID 25788273, 2015). "However, in other instances, DKK1 was found to be repressed in certain colon cancers and it was suggested that DKK1 might act as a tumor suppressor gene." (PMID 26545120, 2015). "Previous studies have shown that the expression of DKK-1 was down-regulated significantly in human colon cancer, gastric cancer and melanoma, suggesting that DKK-1 may act as a tumor suppressor in these cancers and its role as an antagonist of Wnt signaling is lost in these cancers." (PMID 24612589, 2014).
colon carcinoma (continued). "However, paradoxically, the expression of DKK-1 was down-regulated significantly in human colon cancer, gastric cancer and melanoma, suggesting that the function of DKK-1 may be different in different types of cancers." (PMID 25116444, 2014). "Thus, the induction of DKK-1 expression by 1,25(OH)2D3 found in cultured cells and animal models may contribute to restore DKK-1 expression and antitumor effects in human colon cancer." (PMID 24202444, 2013). "Complementing this, a synthetic LRP antagonist, RRP‐Dkk1c is developed, which exhibits heightened effectiveness in attenuating Wnt/β‐catenin signaling activity compared to Dkk1, thereby abolishing the formation of CT26‐derived colon cancer xenograft in vivo." (PMID 40152621, 2026). "In colon cancer cells and HCC tissues, miR-217 directly interacted with the 3′-UTR of DKK1 and diminished DKK1 expression, constitutively activating Wnt signaling and promoting the tumorigenesis and progression of HCC." (PMID 35355709, 2022). "By contrast, a recent study indicates that preoperative serum levels of DKK-1 protein seem to be a predictive marker of tumor invasion and relapse in stage II-III colon cancer." (PMID 25788273, 2015). "Here, we validated that Wnt pathway genes such as DKK-1, DVL-1 and Wnt10A are indeed positively regulated by Fra-1 in both HT29 and HCT15 colon cancer cell lines." (PMID 26646695, 2015). "Qi and colleagues have demonstrated the ability of Dickkopf-1 (Dkk1), a potent Wnt signaling inhibitor, to reverse EMT in colon cancer." (PMID 24527460, 2014). "In contrast, expression of the DKK-1 gene, a downstream target of β-catenin/TCF, decreases in human colon tumors, indicating its tumor suppressing role in this neoplasia." (PMID 21029453, 2010). "In colon cancer cell lines where DKK-1 is epigenetically silenced, forced expression of DKK-1 inhibits proliferation and reduces xenograft tumor growth." (PMID 21317455, 2010). "DNA methylation assays showed that genistein treatment did not affect the methylation status of the DKK1 promoter in any of the tested colon cancer cell lines, suggesting that DNA methylation is not responsible for genistein-induced DKK1 expression." (PMID 40969596, 2025). "DKK1, a target of WNT, has been convinced to be a biomarker for predicting colon cancer recurrence and give suggestions for adjuvant therapy stratification in stage II colon cancer." (PMID 33996273, 2021). "Furthermore, overexpression of HOXC6 promoted the migration and invasion of colon cancer cells through inducing EMT by activating the Wnt/β-catenin signaling pathway and inhibition of DKK1 secretion." (PMID 33795652, 2021). "GEN treatment led to re-expression of DKK1 in SW480 and HCT-15 cell lines, whereas mRNA levels were not affected in other colon cancer cell lines, especially those with extensive DKK1 promoter methylation (RKO, SW48, DLD-1)." (PMID 25322458, 2014). "Contrary to human homologues DKK1 and DKK2, whose silencing by CGI hypermethylation is indicated both in colon cancer cell lines and gastrointestinal tumors, Dkk1 downregulation in mice has been suggested to occur through factors independent of DNA hypermethylation." (PMID 24204690, 2013). "However, DKK-1 seems to have antitumor effects independent of β-catenin/TCF transcriptional inhibition, as DKK-1 overexpression in APC-mutant colon cancer cells decreases colony formation capacity in vitro and tumor growth in immunodeficient mice." (PMID 24202444, 2013). "In addition, DKK1 was reported to be a downstream target of β-catenin/T-cell factor and participates in a negative feedback loop in the Wnt signaling in colon cancer cells." (PMID 24391982, 2013). "This might involve the upregulation of WNT inhibitors (e.g. DKK1 and SFRP1) as observed in metastatic vs. non-metastatic colon cancer patients, but also oncogene-mediated increases in GLI function and cell-intrinsic metastatic reprogramming." (PMID 31253868, 2019).
hepatocellular carcinoma (58 papers, 2010 to 2025). A malignant tumor that arises from hepatocytes. "Contrasting results demonstrate that whilst overexpression of DKK1 is linked with migration and invasion of hepatocellular carcinoma, DKK1 inhibits migration and invasion of colon and breast cancer." (PMID 38036593, 2023). "Recent meta-analyses validated the role of DKK-1 and its use as diagnostic and prognostic factors in hepatocellular carcinoma and gastric cancer." (PMID 34451907, 2021). "Recently several reports have indicated that elevated expression of DKK1 is tightly associated with the progression of hepatocellular carcinoma (HCC)." (PMID 24325363, 2013). "Moreover, DKK1 has been implicated in hepatocellular carcinoma tumorigenesis by activating the Wnt/β-catenin signaling pathway." (PMID 39505867, 2024). "In addition, DKK1 has a more significant diagnostic value than AFP in hepatocellular carcinoma." (PMID 37017469, 2023). "Lower expression of DKK1 in colorectal cancer downregulated VEGF, while higher expression of DKK1 was associated with higher expression of VEGF in hepatocellular carcinoma and cholangiocarcinoma." (PMID 39795613, 2025). "In hepatocellular carcinoma, inhibition of DKK1 enhances the anti-tumor efficacy of sorafenib via inhibition of the PI3K/Akt and Wnt/β-catenin pathways." (PMID 38376441, 2024). "Previous studies have shown that DKK1 promotes malignant phenotypes in hepatocellular carcinoma, including tumor angiogenesis, invasion, and metastasis." (PMID 37017469, 2023). "In hepatocellular carcinoma, DKK1 promotes tumorigenesis, including invasion, metastasis, and angiogenesis, and is associated with poor prognosis." (PMID 37017469, 2023). "Overexpression of DKK-1 has been shown to predict poor prognosis for patients with hepatocellular carcinoma after liver transplantation by promoting cancer metastasis and recurrence." (PMID 37511813, 2023). "Some reports indicate that DKK1 is a tumour promoter in pancreatic cancer, oesophageal cancer, and hepatocellular carcinoma." (PMID 35907982, 2022). "The clinical and prognostic significance of DKK-1 has been reported in breast cancer, lung cancer, esophageal cancer, myeloma, pancreatic cancer, and hepatocellular carcinoma." (PMID 33921232, 2021). "Previous studies have shown that DKK1 expression is up-regulated in solid tumors such as hepatocellular carcinoma and ESCC." (PMID 34426559, 2021). "For example, in hepatocellular carcinoma, only one study found decreased DKK-1 levels at mRNA and protein levels together with high levels of the methylation promoter for this gene in human samples." (PMID 34451907, 2021). "For example, serum DKK-1 levels are high in patients with cervical, endometrial cancer, and hepatocellular carcinoma, when compared to controls." (PMID 33921232, 2021). "Among these trials, one study aiming at hepatocellular carcinoma using a humanized monoclonal antibody against Dickkopf-1 (DKK1), DKN-01, is involved in phase I and II trials (ClinicalTrials.gov Identifier: NCT03645980)." (PMID 34591416, 2021). "Consistent with the zymography, qPCR and Western blot results measuring the expression levels of invasion-related genes, recombinant DKK1 promotes the invasion of hepatocellular carcinoma cell lines." (PMID 31568519, 2019). "Our data suggest that TGF-β1 is essential for the cell migration and invasion induced by DKK1 in hepatocellular carcinoma cell lines." (PMID 31568519, 2019). "Our results indicate that recombinant DKK1 has a proinvasive effect that is associated with an exacerbation of the inflammatory process in both the HepG2/C3A and PLC/PRF/5 hepatocellular carcinoma cell lines." (PMID 31568519, 2019). "In hepatocellular carcinoma, high DKK1 mRNA and protein expression was correlated with poor OS and DFS." (PMID 29720122, 2018). "Human hepatoma cells, such as Hep3B and Huh-7, showed high levels of DKK-1 expression, whereas 293 cells and HUVECs showed little or no DKK-1 expression." (PMID 28938611, 2017).
hepatocellular carcinoma (continued). "The postoperative levels of serum DKK‐1 in patients with hepatocellular carcinoma have been shown as a useful surveillance biomarker to evaluate the therapeutic response." (PMID 26988995, 2016). "For instance, DKK1 protein was predominantly elevated in tissues of hepatocellular carcinoma, non-small cell lung cancer and chondrosarcoma." (PMID 27457487, 2016). "Our results confirmed literature data reporting the role of DKK-1 as a potential serological biomarker in different tumors such as gastric cancer, hepatocellular carcinoma, non-small cell lung cancer and gynaecological cancer." (PMID 24655661, 2014). "Of note, Bel7402 hepatocellular carcinoma cells exhibited the highest level of DKK1 in both mRNA and protein level." (PMID 24325363, 2013). "But vice versa, reduction of DKK1 expression by RNA interference is able to increase the migration in a model of hepatocellular carcinoma cells." (PMID 24325363, 2013). "We employed this method to determine the affinity of DS4 towards unpurified native human DKK1 contained in conditioned media from the hepatic carcinoma cell line Hep3B." (PMID 22558410, 2012). "Our cell cultures express DKK1 at high levels, like other tumors such as Wilms' tumor, osteosarcomas, hepatocellular carcinomas and prostate cancer." (PMID 20175889, 2010). "In addition, several reports have shown that DKK1 is correlated with the progression of hepatocellular carcinoma by inducing angiogenesis or metastasis." (PMID 40025612, 2025). "In hepatocellular carcinoma, DKK1′s interaction with CKAP4 increases PD-L1 expression as well." (PMID 41149482, 2025). "DKK-1 promotes angiogenesis and is a biomarker for hepatic stem cell-like hepatocellular carcinoma." (PMID 37511813, 2023). "Overexpression of miR‐522 could promote proliferation of hepatocellular carcinoma through repressing DKK1 and SFRP2." (PMID 33369228, 2021). "The combined detection of serum AFP and secreted protein DKK1 could be used as an important way to improve the sensitivity and accuracy of clinical diagnosis of primary hepatic carcinoma." (PMID 31428352, 2019). "However, several tumor studies revealed that high DKK1 expression is correlated with activation of the Wnt/β-catenin pathway in both hepatocellular carcinoma and hilar cholangiocarcinoma." (PMID 29720122, 2018). "In addition, DKK-1 is highly expressed in hepatocellular carcinoma (HCC), which is significantly correlated with poorer pathologic grade and postoperative outcomes." (PMID 28938611, 2017). "Besides, serum DKK1 is found to serve as a novel protein biomarker for the diagnosis of hepatocellular carcinoma." (PMID 26908452, 2016). "For example, it has been suggested that DKK1 could be used as a prognostic marker and therapeutic target for hepatocellular carcinoma." (PMID 26545120, 2015). "Apart from DKK1's role as a Wnt-signaling antagonist, DKK1 overexpression correlates to an accumulation of β-catenin in the cytoplasm or nucleus in clinical samples from hepatocellular carcinoma." (PMID 26353782, 2015). "However, DKK-1 is remarkably overexpressed in myriad tumor types including hepatocellular carcinoma and osteosarcoma." (PMID 25144498, 2014). "Because DKK1 has been reported as an important marker of hepatocellular carcinoma, we reasoned that this pathway could be significantly involved in liver cancer metastasis and invasion." (PMID 24324730, 2013). "Importantly, however, abundant DKK1 expression may promote hepatocellular carcinoma cell migration and invasion, and serve as a protein biomarker of liver cancers." (PMID 38529014, 2024). "For example, some reports discovered that DKK1 was overexpressed in hepatocellular carcinoma (HCC) and myeloma, acting as a tumor promoter." (PMID 31285694, 2019). "However, paradoxically, DKK-1 has been found to be overexpressed in hepatoblastomas, hepatocellular carcinomas, and Wilms’ tumors, suggesting that the function of DKK-1 may be different in different cancers." (PMID 24612589, 2014).